VTN (vitronectin)
Description:
Vitronectin is a cell adhesion and spreading factor found in serum and tissues. Vitronectin interact with glycosaminoglycans and proteoglycans. Is recognized by certain members of the integrin family and serves as a cell-to-substrate adhesion molecule. Inhibitor of the membrane-damaging effect of the terminal cytolytic complement pathway. Somatomedin-B is a growth hormone-dependent serum factor with protease-inhibiting activity.
Synonyms: VN; V75; VNT
Tractability: Small molecule: a structure with a bound ligand is known; it has a binding pocket of medium quality. Antibody: UniProt places it where antibodies can reach, with high confidence; its Gene Ontology location is reachable by antibodies, with high confidence; UniProt predicts a signal peptide or a membrane-spanning region. PROTAC: its protein half-life has been measured.
Target class: Adhesion
Gene: Protein-coding gene on chromosome 17 (28,367,265 to 28,373,091, reverse strand). Ensembl gene ENSG00000109072.
Subcellular location: Secreted, extracellular space; Parasitophorous vacuole
Subcellular location (Human Protein Atlas): Endoplasmic reticulum; Vesicles; Predicted to be secreted
Pathways (Reactome):
Extracellular matrix organization: ECM proteoglycans; Integrin cell surface interactions; Molecules associated with elastic fibres; Syndecan interactions
Developmental Biology: Developmental Lineage of Pancreatic Ductal Cells
Disease: Dengue virus activates/modulates innate and adaptive immune responses
Immune System: Regulation of Complement cascade
Gene Ontology:
Molecular function: cell-matrix adhesion mediator activity; integrin binding; protein binding; extracellular matrix binding; extracellular matrix structural constituent; collagen binding; heparin binding; identical protein binding; polysaccharide binding; scavenger receptor activity
Biological process: cell adhesion mediated by integrin; cell migration; cell-matrix adhesion; endodermal cell differentiation; integrin-mediated signaling pathway; negative regulation of blood coagulation; negative regulation of proteolysis; positive regulation of integrin-mediated signaling pathway; positive regulation of receptor-mediated endocytosis; positive regulation of smooth muscle cell migration; positive regulation of vascular endothelial growth factor signaling pathway; regulation of cell adhesion; smooth muscle cell-matrix adhesion; cell adhesion; immune response; negative regulation of fibrinolysis; positive regulation of vascular endothelial growth factor receptor signaling pathway; positive regulation of wound healing; cell differentiation; liver regeneration; oligodendrocyte differentiation; protein polymerization; vesicle-mediated transport
Cellular component: blood microparticle; endoplasmic reticulum; extracellular exosome; extracellular matrix; extracellular region; peptidase inhibitor complex; protein complex involved in cell-matrix adhesion; symbiont-containing vacuole; alphav-beta3 integrin-vitronectin complex; microfibril; basement membrane; Golgi lumen; rough endoplasmic reticulum lumen
Genetic constraint (gnomAD): Loss-of-function variants: 48 observed, 58.81 expected, observed/expected ratio (o/e) 0.82, 90% interval 0.65 to 1.04. The upper end of that interval is the gene's LOEUF score, 1.04, which puts it in group 4 of 6, group 1 being the genes least tolerant of losing a copy. Missense variants: 589 observed, 650.77 expected, observed/expected ratio (o/e) 0.91, 90% interval 0.85 to 0.97. Synonymous variants: 238 observed, 247.15 expected, observed/expected ratio (o/e) 0.96, 90% interval 0.87 to 1.07.
Homologues: Orthologues: chimpanzee VTN (99% identical), macaque VTN (86% identical), rabbit VTN (76% identical), mouse Vtn (74% identical), guinea pig VTN (74% identical), rat Vtn (73% identical), dog VTN (71% identical), pig VTN (63% identical), zebrafish vtna (42% identical), tropical clawed frog vtn (41% identical), zebrafish vtnb (40% identical). Paralogues in human: PRG4 (26% identical).
Diseases named in the same sentence as VTN in open-access papers:
VTN is named in the same sentence as 177 diseases in open-access papers, as found by Europe PMC text mining. Sharing a sentence is not in itself a finding about the gene and the disease. The quoted sentences say what the papers report.
breast carcinoma (34 papers, 1997 to 2025). "Previous studies of vitronectin indicate that it has been linked to various forms of cancers that includes ovarian cancer, prostate cancer, cervical cancer, neuroblastoma, and breast cancer." (PMID 33211735, 2020). "In the presence of vitronectin (VN) as underlying adhesive matrix, both wt breast cancer cell lines enhanced adhesion." (PMID 29464079, 2018). "Gal-3 overexpression in human breast carcinoma cell lines increases their adhesion to vitronectin, fibronectin, and laminin, which protects them from apoptosis." (PMID 40566589, 2025). "Vitronectin concentration levels were involved and connected to the tumor recurrence and metastasis of breast cancer." (PMID 39717749, 2024). "By analyzing TCGA bulk tissue RNA profiles, we found that dual enhancement of VTN and C1QBP was associated with a worse prognosis in basal-like breast cancer patients compared to patients with high or low expression of either gene." (PMID 38773982, 2024). "We further established an ECM signature based on the fibrinogen/fibronectin/vitronectin/elastin axis, which efficiently predicts patient prognosis in breast cancer." (PMID 37369642, 2023). "The expression data of ECM fiber-encoding genes (e.g., COL1A1, COL1A2, FGA, FGB, FGG, ELN, FN1, and VTN) from 1358 patients with breast cancer were used for Kaplan–Meier overall survival analysis." (PMID 37369642, 2023). "In our study, we constructed and validated an ECM signature consisting of the expression of fibrinogen, elastin, fibronectin, and vitronectin to effectively predict clinical outcomes in patients with breast cancer." (PMID 37369642, 2023). "There are also RNA aptamers targeting PAI-1 which block its interaction with vitronectin, and play a role in anti-metastasis in an in vitro breast cancer cell model 54,55." (PMID 36605486, 2023). "Core fucosylation of these molecules played important functions in breast cancer cell adhesion to vitronectin and their responsiveness to IL-6 or oncostatin M (OSM) signaling." (PMID 35303925, 2022). "SM-20 increased cellular adhesion in breast cancer cells by limiting vitronectin detachment from breast cancer cells in the presence of PAI-1." (PMID 33918821, 2021). "We believe that vitronectin concentration levels are involved and connected to the metastasis of breast cancer in certain patients, specifically based on recurrence or ethnicity, which is detrimental for poor prognosis." (PMID 33211735, 2020). "A previous study compared the relationship between Integrin αvβ3 and vitronectin, and considered if the two can be used together or separately as a biomarker for higher stages of breast cancer." (PMID 33211735, 2020). "In this study, we focused on the role of vitronectin in breast cancer survival and its functional role as a non-invasive biomarker for early stage and stage specific breast cancer detection." (PMID 33211735, 2020). "First, we validated its effectiveness in our own hands to block MDA-MB-231 breast cancer cell binding to vitronectin, an interaction that specifically requires SDC1-ITGαvβ3 complexes." (PMID 32760722, 2020). "After running the SimpleWestern, analysis of the vitronectin and other regulating proteins concentration levels in breast cancer cell lines revealed that PI3K and P-AKT regulate vitronectin concentration levels in BC cell lines." (PMID 33211735, 2020). "An earlier work on adhesion of breast carcinoma cells to the extracellular matrix molecules e.g., vitronectin and fibronectin reported a significant decrease in adhesion after exposure to hypoxia." (PMID 29949925, 2018). "We have identified a vitronectin stimulated signaling axis that leads to phosphorylation and stabilization of FRA-1, which is associated with increased transcriptional activity and breast cancer invasion." (PMID 29382358, 2018).
breast carcinoma (continued). "In clinical samples, a molecular component signature consisting of vitronectin-uPAR-uPA-FRA-1 predicts poor overall survival in patients with breast cancer and correlates with an FRA-1 transcriptional signature." (PMID 29382358, 2018). "The insulin-like growth factor (IGF)-I: IGF binding protein (IGFBP):vitronectin complexes have been shown to stimulate changes in gene expression favouring increased breast cancer cell survival and a migratory phenotype." (PMID 25167778, 2014). "Inhibition of uPA secretion will reduce the formation of uPA–uPAR–αVβ3–vitronectin complex, with the consequent suppression of adhesion and migration of invasive breast cancer cells." (PMID 18362935, 2008). "Secreted uPA can bind to uPAR and forms a complex with integrin receptor αVβ3, which through its interaction with vitronectin is involved in adhesion and migration of breast cancer cells." (PMID 18362935, 2008). "Integrin receptor αVβ3 is involved in adhesion of breast cancer cells through its interaction with extracellular matrix (ECM) protein vitronectin." (PMID 18362935, 2008). "αvβ3 integrin-mediated migration of bone metastatic mammary carcinoma cells towards vitronectin is therefore dependent, in part, on extracellular protease activity." (PMID 16608535, 2006). "We also tested the effect of the propofol-DHA and propofol-EPA conjugates on adhesion of the breast cancer cells to a vitronectin substrate." (PMID 16168109, 2005). "The conjugates were tested for their ability to inhibit breast cancer cell migration, alter adhesion to the matrix protein vitronectin and induce apoptosis." (PMID 16168109, 2005). "In vitro, bone marrow-derived endothelial precursor cells from four human breast cancer xenografts proliferated and formed multiple clusters of spindle-shaped attaching cells on a vitronectin-coated dish." (PMID 12454777, 2002). "From clinical research, studies have shown that there was significantly higher level of serum VTN in breast cancer patients with early stage than those in healthy people, patients with benign breast lesions or pre-cancerous lesions, and advanced breast cancer patients." (PMID 39717749, 2024). "Conceivably, the influence of the αvβ3 integrin in breast cancer cells extends beyond its function as a membrane thyroid hormone receptor and is mediated through other ligands of the extracellular matrix, such as the canonical ligand vitronectin." (PMID 35160139, 2022). "Moreover, changes in vitronectin levels were observed in response to calcification of the aortic valve as well as in the course of breast cancer development." (PMID 35990326, 2022). "PAI-1 binds vitronectin on the surface of breast cancer cells, a critical step in metastasis." (PMID 33918821, 2021). "Based on the findings of genomic data analysis we hypothesized that concentration of vitronectin in serum could be a prognostic marker for breast cancer patients." (PMID 33211735, 2020). "However, when isolating just the breast cancer cell lines, we found that there are more cell lines with vitronectin copy number amplified than in any other cancer cell line." (PMID 33211735, 2020). "Indeed, vitronectin can stimulate increased tumor cell invasion and promote tumor growth of breast cancer cells." (PMID 29382358, 2018). "Vitronectin is also reported to be a possible biomarker for stage 0–1 breast cancer with AUC 0.73." (PMID 28687783, 2017). "Therefore, in this current study we showed that the serum vitronectin levels could be an early marker for the breast cancer survival and we also determine the cellular signaling factors which modulate the expression and concentration of vitronectin." (PMID 33211735, 2020). "Fibronectin, vitronectin and collagen I are among the most abundant extracellular matrix proteins and are among the key ligands of the crucial adhesion-regulating integrins, therefore, the influence norepinephrine has on breast cancer cells adhering to these substrates was investigated." (PMID 32098331, 2020).
breast carcinoma (continued). "Core fucosylation of these molecules plays important functions in breast cancer cell adhesion to vitronectin, and their responsiveness to IL-6 or OSM signaling is involved in breast cancer EMT and metastasis." (PMID 35303925, 2022). "In addition, we showed that core fucosylation of integrin αvβ5 or IL6ST might be crucial for breast cancer cell adhesion to vitronectin or enhanced cellular signaling to interleukin 6 and oncostatin M, two cytokines implicated in the breast cancer epithelial–mesenchymal transition and metastasis." (PMID 35303925, 2022). "Since vitronectin prominently accumulates in the ECM of tumor cells of various carcinomas, especially breast cancer cells." (PMID 33211735, 2020). "The cellular data from four different breast cancer cell lines- MCF7, MDA-MB-231, MDA-MB-468, and HCC1599 indicated that the PI3K/AKT axis is modulating the expression of vitronectin." (PMID 33211735, 2020). "Here we have described a vitronectin-stimulated pathway that leads to increased FRA-1 phosphorylation, transcriptional activity and invasion in basal-like breast cancer cells." (PMID 29382358, 2018). "Transient knockdown of urokinase/plasminogen activator urokinase receptor (uPAR) in basal-like breast cancer cells grown on vitronectin reduces FRA-1 phosphorylation and stabilization; and uPAR and FRA-1 are required for vitronectin-induced cell invasion." (PMID 29382358, 2018). "GDE3 suppressess the vitronectin- and uPAR-dependent transformed phenotype of MDA-MB-231 breast cancer cells." (PMID 28849762, 2017). "Breast cancer cells express integrin receptor αVβ3, which through its interaction with an extracellular matrix (ECM) protein vitronectin, contributes to the cancer cell adhesion and migration." (PMID 22479587, 2012). "MCF7 human breast cancer cell line was used as control which did not exhibit much of VTN upregulation under serum deprivation." (PMID 32429996, 2020). "GDE3 suppresses the vitronectin- and uPAR-dependent phenotype of MDA-MB-231 breast cancer cells." (PMID 28849762, 2017). "Adhesion to fibronectin, vitronectin and laminin, but not type IV collagen, was influenced by the inhibitor arginine-glycine-aspartate, suggesting that breast cancer cell recognition of collagen IV is mediated through alternative epitopes." (PMID 9043016, 1997). "In MCF-7 breast cancer cells, PAK4 expression increased migration of the cells on vitronectin, another extracellular matrix protein, and inhibited cell spreading and adhesion to vitronectin by stimulating integrin avβ5 and specifically phosphorylating integrin β544–46." (PMID 33051544, 2020).
ovarian carcinoma (25 papers, 2010 to 2025). A malignant neoplasm originating from the surface ovarian epithelium. "Previous studies predominantly demonstrate that VTN is an oncogenic factor that advances tumor progression in a variety of malignancies, including breast and ovarian cancers, through multiple mechanisms." (PMID 40433359, 2025). "In parallel with these studies, it has been shown that exosomal miR-99a-5p is elevated in the serum of ovarian cancer patients and promotes cancer cell invasion by increasing fibronectin and vitronectin expression in adjacent peritoneal mesothelial cells." (PMID 38916832, 2024). "Vitronectin promotes adhesion and chemoattraction in ovarian cancer cells via the α5β1 and αvβ3 integrins and the urokinase plasminogen activator surface receptor." (PMID 35740424, 2022). "Suppressor in ovarian cancer by inhibiting αvβ3integrin/vitronectin-mediated cell motility and proliferation.Suppressor in lung cancer by regulation of β1 integrin maturation." (PMID 34830819, 2021). "In a variety of tumors, such as cervix neoplasia, ovarian cancer, and prostate cancer, VTN was considered a promising biomarker, which encoded vitronectin, an adhesive glycoprotein that connected cells with ECM." (PMID 33178362, 2020). "Numerous previous studies have revealed that both fibronectin and vitronectin play important roles in peritoneal dissemination of ovarian cancer." (PMID 30396333, 2018). "HPMCs transfected with miR-99a-5p promoted ovarian cancer invasion and exhibited increased expression levels of fibronectin and vitronectin." (PMID 30396333, 2018). "The mechanisms responsible are related to MMP-2-mediated cleavage of vitronectin and fibronectin to generate fragments that interact with integrin receptors α5β1 and αvβ3, which promote the adhesion of ovarian cancer cells lining the peritoneal cavity." (PMID 27634880, 2016). "Specifically, vitronectin has been shown to promote invasiveness of ovarian cancer cells and their spread in the peritoneum." (PMID 27634880, 2016). "Our list of peptides found in ovarian cancer specimens includes fragments derived from the proteins vitronectin, transketolase and haptoglobin." (PMID 24694173, 2014). "Moreover, VTN and fibronectin in ascites promoted cell adhesion and performed indispensable in peritoneal metastasis of ovarian cancer." (PMID 39717749, 2024). "Among them, MMP9 regulates cell–cell adhesion by catalyzing E-cadherin ectodomain shedding to mediate metastatic dissemination, whereas MMP2 mediates the peritoneal adhesion of ovarian cancer cells by cleaving the extracellular matrix proteins fibronectin and vitronectin into small fragments." (PMID 35860572, 2022). "In line with this hypothesis, FZD-5 increased adhesion to FN and vitronectin in ovarian cancer cells." (PMID 33723319, 2021). "In agreement with the notion that vitronectin is the main mesothelium-associated ligand, SKOV-3 ovarian cancer and primary EOC cells, the last derived from a human HGSC tissue sample, markedly adhere to Vn matrices as well as to a re-constructed mesothelial layer." (PMID 31703596, 2019). "Exosomal miR-99a-5p from EOC cells promotes cell invasion by affecting HPMCs through fibronectin and vitronectin upregulation and may serve as a target for inhibiting ovarian cancer progression." (PMID 30396333, 2018). "IMD-4482 inhibited in vitro cell adhesion to vitronectin in PAI-1-positive ovarian cancer cells, followed by the inhibition of extracellular signal-regulated kinase and focal adhesion kinase phosphorylation through dissociation of the PAI-urokinase receptor complex from integrin αVβ3." (PMID 29163796, 2017). "Up-regulated VTN expression could stimulate ovarian cancer cell migration." (PMID 39717749, 2024).
ovarian carcinoma (continued). "Exosomal miR‐99a‐5p derived from ovarian cancer cells promotes tumour invasion and metastasis by regulating the expression of fibronectin and vitronectin in HMrSV5 cells, suggesting biological cargos derived from exosome could perform important effects on recipient cells." (PMID 34725902, 2021). "Other soluble ECM proteins, such as vitronectin (the 11th), SERPIND1 (the 38th), and periostin (the 112th), also exhibit different oncogenic activities in ovarian cancer." (PMID 35740424, 2022). "The effect of SRO-91 or RBV treatment on vitronectin expression, main receptor of αv integrins, or laminin another matrix protein, did not act on the organization of the extracellular matrix of ovarian cancer cells." (PMID 31825993, 2019). "In contrast, they reported elevated levels of a number of proteins (e.g., hemopexin, histidine-rich glycoprotein, and vitronectin) that were identified in our study but did not meet our criteria for overexpression in ovarian cancer serum." (PMID 20546617, 2010). "Several genes found in our analysis have previously been described as biomarkers of ovarian cancer or potential therapeutic targets, including genes from the ITGA and ITGB superfamily, laminins, fibroblast growth factors, collagens, insulin growth factors, EGFR, FN1, EPHA2, TNC, SPP1, and VTN." (PMID 36352420, 2022).